CTSG (cathepsin G)
Diseases named in the same sentence as CTSG in open-access papers (continued):
Sharing a sentence is not in itself a finding about the gene and the disease.
infection (continued). "This gene encodes a serine protease inhibitor that specifically inhibits neutrophil elastase, cathepsin G, and proteinase-3 present in the neutrophil granules; thus, protecting not only tissues from damage at inflammatory sites during stress or infection, but also the neutrophil itself." (PMID 33746962, 2021). "During infection with S. aureus, a substantial release of neutrophilic proteases (including elastase or cathepsin G) may occur." (PMID 34663090, 2021). "As the infection progresses, this protective layer may be compromised by P. aeruginosa products such as elastase B or host inflammatory factors such as cathepsin G, neutrophil elastase, and proteinase-3, all of which degrade surfactant protein SP-A." (PMID 26090668, 2015). "These granular enzymes vary with cell type but include elastase, myeloperoxidase, lysozyme, and cathepsin G. Various clinical studies have demonstrated that collectively, these enzymes, are sensitive and reliable markers of both early-onset phases and established infections." (PMID 36292097, 2022). "None of the major neutrophil effector molecules Elastase (ELANE), Proteinase 3 (PRTN3), Cathepsin G (CTSG) and Myeloperoxidase (MPO) changed significantly in response to infection." (PMID 38472281, 2024). "Activated neutrophils exocytose neutrophil serine proteases (NSPs), such as neutrophil elastase (NE), proteinase 3 (PR3), cathepsin G (CatG), and neutrophil serine protease 4 (NSP4), at the site of infection." (PMID 36144551, 2022). "These include three proteases that are upregulated during the course of infection: the matrix metalloprotease MMP9, the serine proteases neutrophil elastase (ELANE), and cathepsin G (CTSG), as well as the protease inhibitor SERPINB1." (PMID 23638192, 2013). "Statistically significant protein alterations of PRTN3, MPO, ELANE, CTSG, and AZU1 dysregulation is important in the early phases of infection and may be targets for anti-SARS-CoV-2 therapeutics." (PMID 33079950, 2020). "Human cathepsin G can also activate coagulation factor VIII, which may contribute to the enhanced coagulation in areas of infection where neutrophils accumulate." (PMID 29652924, 2018). "In IL-13tg mice, cathepsin G gene expression was not altered after infection with Mtb (data not shown)." (PMID 24979482, 2014). "Therefore, the lysosomal enzyme (cathepsin G and cathepsin D), CFH metabolites (LVV-H7), and angiotensin II may act as different indicators to guide clinical infection outcomes, including sepsis, shock, or septic shock." (PMID 39767696, 2024). "The identified up-regulated proteins Myeloperoxidase, Myeloblastin, Neutrophil Elastase, Cathepsin G, and Azurocidin (MPO, PRTN3, ELANE, CTSG, and AZU1) in naso-oropharyngeal swab samples are discussed to highlight the molecular mechanism changes in the site of infection." (PMID 33079950, 2020). "Whereas elastase is primarily required for clearance of certain Gram-negative bacteria, cathepsin G has been shown to be effective against infection with Gram-positive bacteria including Streptococcus pneumoniae and Staphylococcus aureus, as well as certain fungal infections." (PMID 28507954, 2017).
bacterial infection (5 papers, 2015 to 2025). "In diabetic dermis, the upregulation of CTSG, MMP9, and MMP1 may depend on bacterial infection at the site of DFU and on a dysregulation of growth factors." (PMID 31315286, 2019).
CNS tumors (1 paper, 2021). "Early studies on the capacity of NET-related proteins such as elastase, proteinase-3, and cathepsin G to invade CNS tumors preliminarily showed traces of NETs in CNS tumors." (PMID 34336122, 2021).
digestive system tumors (1 paper, 2024). "This analysis encompassed a total of nine cathepsins include cathepsin B, cathepsin E, cathepsin F, cathepsin G, cathepsin H, cathepsin L2, cathepsin O, cathepsin S, and cathepsin Z, and six digestive system tumors (HCC, PCa, BTC, CRC, GC, and EC)." (PMID 38590662, 2024).
inflammation (1 paper, 2024). Aberrant reaction of the microcirculation characterized by movement of fluid and leukocytes from the blood into extravascular tissues. "The association of CTSG with lung inflammation has even implicated CTSG as a potential biomarker for airway tissue damage." (PMID 38791530, 2024). "Like NE, CTSG has several important roles in cellular and immune functions related to lung inflammation, such as cytokine processing, pathogen clearance, and cell-surface receptor modification." (PMID 38791530, 2024).
CTSG also shares sentences with these, for which no sentence is quoted: type 1 diabetes (4 papers); acute respiratory distress syndrome (3); bladder cancer (3); systemic lupus erythematosus (3); type 2 diabetes (3); acute monocytic leukemia (2); adenocarcinoma (2); cardiovascular diseases (2); co-infection (2); Crohn disease (2); esophageal carcinoma (2); myeloproliferative diseases (2); neurodegenerative disease (2); pressure ulcers (2); acute leukemia (1); Allergy (1); ANCA-associated vasculitis (1); aneurysm (1); aortic valve disease (1); Arterial thrombosis (1); autoimmune hepatitis (1); B-cell lymphoma (1); bone metastasis (1); brain disorder (1); breast invasive carcinoma (1); Candida infection (1); cardiomyopathy (1); cerebral artery occlusion (1); cervical cancer (1); cervical squamous cell carcinoma (1).
A further 55 diseases each share a sentence with CTSG in 1 paper.